AGT (angiotensinogen)
Diseases named in the same sentence as AGT in open-access papers (continued):
Sharing a sentence is not in itself a finding about the gene and the disease.
Myocardial fibrosis (307 papers, 2010 to 2026). "C3 AGT + Fibroblasts exhibit increased sensitivity towards adverse outcomes in cardiomyopathy, such as myocardial fibrosis and impaired cardiac contractile function, compared to other cardiac fibroblast subpopulations." (PMID 38799173, 2024). "There are also the results of enrichment pathway by GO_BP enrichment analysis and all the differential genes of this subgroup, all three of which indicate that C3 AGT + Fibroblasts are more active for the progression of cardiomyopathy and myocardial fibrosis." (PMID 38799173, 2024). "By the most important nodes and ranked by centrality scores, the most important shared elements for myocardial fibrosis and HCM were calcium, TGF-β, collagen, AGT encoding angiotensinogen, angiotensin II, AMPK, cell population proliferation, inflammatory response, and apoptosis." (PMID 34440529, 2021). "Secondly, central fat distribution, which has been assumed to be the metabolically active compartment of fat deposits, could mediate increased LVM through the effects of expression of circulating inflammatory cytokines, elevated availability of angiotensinogen, and increased myocardial fibrosis." (PMID 29631555, 2018).
Obesity (280 papers, 2005 to 2026). Accumulation of substantial excess body fat. "Polymorphism of AGT M235T and T174M can cause the conversion of pre-adipocytes to adipocytes and increase the number and volume of adipocytes which leads to obesity." (PMID 36557328, 2022). "Other diseases such as depression, obesity, diabetic nephropathy, pre-eclampsia, and liver injury are also associated with some variants of AGT gene." (PMID 36557328, 2022). "Another study shows the significant association of AGT M235T gene polymorphism with obesity in females as compared to that in males among the Poland population." (PMID 36557328, 2022). "The gender specific study showed the significant association of AGT M235T gene polymorphism with obesity in males as compared to that in females among the Tunisian population." (PMID 36557328, 2022). "Angiotensinogen is produced in the liver and is upregulated in adipocytes in obesity, while adipocyte angiotensin deficiency can prevent hypertension in the obese populations." (PMID 32708430, 2020). "Local RAS in adipocytes is activated during obesity in humans and adipocyte-specific deficiency of angiotensinogen prevented the obesity-induced increase in plasma levels of ANG II." (PMID 30064425, 2018). "Tiago has recently elegantly demonstrated the interactionof obesity with an angiotensinogen mutation." (PMID 17940670, 2007). "In our study population, the prevalence of overweight/obesity is strongly expressed, and the modulating effect of the AGT genetic variants may be consistent with this feature." (PMID 35886041, 2022). "Many studies showed a significant association of AGT polymorphism with obesity." (PMID 36557328, 2022). "However, as previously reported, data on AGT polymorphism’s influence on obesity are scarce in the literature, while this gene polymorphism’s effects on blood pressure are well established." (PMID 31365628, 2019). "In addition, AT2R deficiency in male mice protects against obesity induced by adipose angiotensinogen overexpression, as well as adipose tissue deletion during prolonged fasting." (PMID 31262355, 2019). "We have also investigated AGT polymorphism’s influence on overweight and obesity." (PMID 31365628, 2019). "In obesity, there is an increased production of free fatty acids, angiotensinogen, leptin, resistin and inflammatory mediators that might be involved in mechanisms of obesity-associated microvascular dysfunction." (PMID 25036223, 2014). "Additionally, AT2R deficient mice are protected against obesity that is induced by adipose tissue angiotensinogen overexpression, showing that AT2R plays a major role in mediating local Ang II action on fat mass enlargement." (PMID 23894285, 2013). "On the other hand, Takakura at al. demonstrated that the T/T genotype of the M235T AGT gene polymorphism is linked to visceral obesity and insulin resistance in obese Japanese women, and this genotype is regarded to have greater risk for obesity-related diseases in obese Japanese women." (PMID 35886041, 2022). "In obesity patients, pro-inflammatory and vasoactive adipokines such as angiotensinogen, angiotensin II, aldosterone, and resisting, along with increased plasma renin activity and cytokines are hypersecreted." (PMID 38978621, 2024). "TNF‐α, released by EAT in obesity, was also demonstrated to enhance adipocyte angiotensinogen protein expression and angiotensin II secretion, providing further evidence of the link between obesity and renin‐angiotensin‐aldosterone system activation." (PMID 38156451, 2024). "In our own observation, initially, in the presence of obesity, all patients had high levels of angiotensinogen." (PMID 39683432, 2024). "In obesity, adipose tissue additionally secretes angiotensinogen, which can be converted to Ang II, leading to hyperactivation of the AngI/ACE1/AngII/AT1 arm and subsequent tissue damage." (PMID 37376562, 2023).
Obesity (continued). "In the case of obesity, there is excessive secretion of pro-inflammatory and vasoactive adipokines such as angiotensinogen, angiotensin II, aldosterone, and resisting, along with an increase in plasma renin activity." (PMID 36293177, 2022). "Accordingly, obesity is also characterised by high levels of AGT and angiotensin-converting enzyme (ACE) —two fundamental components of the renin-angiotensin system (RAS)—which plays a central role in the regulation of blood pressure and energy homeostasis." (PMID 35628332, 2022). "In the case of obesity, the adipose tissue can also produce a large amount of angiotensinogen and lead to elevation of the circulating angiotensinogen, which is pretty common in patients with NAFLD." (PMID 36712249, 2022). "The level of circulating AGT and adipogenesis are influenced by adipose tissue derived AGT which then affects the lipid metabolizing capacity of adipocyte and leads to obesity." (PMID 36557328, 2022). "Obesity also favors a deleterious adipocytokine pattern characterized by the overproduction of angiotensinogen and angiotensin II as well as the upregulation of pro-inflammatory cytokines such as interleukin-6, C-reactive protein, and tumor necrosis factor-α." (PMID 34575161, 2021). "Metabolic changes accompanying obesity and insulin resistance increase AGT synthesis and secretion by adipocytes." (PMID 34067712, 2021). "Obesity promotes increased plasma renin activity plasma angiotensinogen and angiotensin-converting enzyme (ACE) activity, promoting enhanced plasma levels of Ang II in obese patients." (PMID 33800427, 2021). "Angiotensinogen and PAI-1 are likely to participate in the vascular complications linked to obesity." (PMID 31456748, 2019). "Researchers have already investigated the AGT expression profile related to obesity; Umemura and cols." (PMID 31365628, 2019). "With the growth of adipose tissue during obesity development, angiotensinogen (Agt), a precursor of angiotensin II that enhances the sympathetic nervous system and blood pressure, is drastically overexpressed." (PMID 30602666, 2018). "The serum levels of almost all components of RAAS are elevated in obesity, and in fact, the amount of adipose tissue present determines the relative amount of circulating angiotensinogen and angiotensin II." (PMID 28993801, 2017). "RAAS activation in obesity has been attributed to increased synthesis of angiotensinogen by visceral fat, renal compression, and increased sympathetic outflows to the kidneys stimulating renin release." (PMID 27857694, 2016). "In obesity, adipocytes also expressed angiotensinogen, leading to an angiotensin II–induced increase in blood pressure." (PMID 26003803, 2015). "In addition, bioactive molecules and hormones associated with obesity (such as leptin, angiotensinogen, aldosterone stimulating factor, dipeptidyl peptidase 4, and resistin) that could explain the metabolic effect of adipose tissue on glomerular hyperfiltration were not measured." (PMID 26495973, 2015). "In fact, enhanced activity of the RAS, represented by increased circulating angiotensinogen, renin, aldosterone, and angiotensin-converting enzyme activity has been reported in obesity." (PMID 25170617, 2014). "Plasma levels of renin activity, angiotensinogen, Ang II, and aldosterone values are elevated during obesity." (PMID 25143800, 2014). "Meta-analysis of the other gene in the rennin-angiotensinogene system, AGT, showed significant association between its polymorphism M235T and CAD, AH, obesity, and stroke; in all cases, the 235T/T genotype is associated with increased risk of diseases." (PMID 22649614, 2009). "Angiotensinogen and PAI-1 are linked to vascular problems associated with obesity." (PMID 40002424, 2025).
Obesity (continued). "The positive association between plasma angiotensinogen (AGT) concentration and body mass index in different human populations also suggests that increased AGT synthesis by adipose mass may contribute to the increased circulating level of AGT in obesity." (PMID 39337664, 2024). "Furthermore, increased expression of angiotensinogen and AngII suggests that activated perivascular fat can contribute to increase BP in obesity by stimulating the local RAAS." (PMID 38186879, 2024). "Obesity and abdominal obesity also cause activation of the RAAS due to the SNS-RAAS interaction, physical compression of the kidney by visceral fat, and the direct release of angiotensinogen by adipocytes." (PMID 38297370, 2024). "Secondly, adipocyte-derived factor, the metabolic alteration in adipose tissue in the setting of obesity, results in an elevated circulating level of adipocyte-derived inflammatory cytokines, enclosing tumor necrosis factor-α, interleukin-6, angiotensinogen, and aldosterone-stimulating factors." (PMID 37464282, 2023). "Some studies have demonstrated that low levels of physical activity lead to insulin resistance, obesity, a reduction in adipocytokines, and an increase in visceral adipocytes that damage the renal vascular system and increase angiotensinogen synthesis, subsequently adversely affecting the kidneys." (PMID 37311642, 2023). "Obesity-associated fat cell hypertrophy has also been related with an increased secretion of angiotensinogen, the precursor of angiotensin II, which may act as a link between obesity and CKD." (PMID 36235590, 2022). "In addition, white adipose tissue is the main extrahepatic source of angiotensinogen, especially in individuals with obesity." (PMID 35684050, 2022). "Obesity is associated with RAAS overactivation, as demonstrated by increased adipose tissue MR expression and elevated plasma levels of aldosterone, renin, angiotensinogen, angiotensin-converting enzyme (ACE), and AT II." (PMID 35043013, 2022). "However, under conditions of obesity, adipose tissue secretes angiotensinogen, which can eventually be converted to Ang-II, leading to hyperactivation of the ACE1/Ang-II/AT1R arm of the RAS and subsequent tissue damage." (PMID 34684358, 2021). "Animal studies have demonstrated up-regulation of angiotensinogen in fatty tissue in obesity." (PMID 33639960, 2021). "Therefore, we performed a population-based study to verify the association between AGT and ACE polymorphisms with overweight/obesity in a general sample of Brazilian adults." (PMID 31365628, 2019). "Thus, the present study aimed to verify the possible association between angiotensinogen (AGT) or angiotensin-converting enzyme (ACE) polymorphisms with overweight and obesity in adults." (PMID 31365628, 2019). "From this perspective, the present study aimed to verify whether the AGT or ACE polymorphisms were associated with overweight and obesity in a population-based study in Brazil." (PMID 31365628, 2019). "Emerging data have revealed that loss of hepatocyte-specific AGT in mice protects against Western diet-induced obesity independent of downstream components of the RAS system." (PMID 31604805, 2019). "Conversely, obesity leads to an overexpression of angiotensinogen and increased blood pressure." (PMID 30364090, 2018). "In fact, menopausal women who successfully lost 5% of their body weight decreased their SBP by 7 mmHg and had lower angiotensinogen, renin, aldosterone, and angiotensin converting enzyme levels, providing experimental evidence for this effective means of treating obesity-related hypertension." (PMID 28993801, 2017). "We therefore conclude that the AGT constitutes an independent risk gene for HTN, obesity and MI, which may be important in the manifestation of CAD associated with these disorders." (PMID 23497386, 2013).
Obesity (continued). "Furthermore, in contrast to rodent models of diet-induced obesity, angiotensinogen mRNA expression in the adipose tissue of obese, hypertensive females is not greater than that of non-obese controls." (PMID 22475205, 2012). "In a study suggesting relation between adipose AGT secretion in obesity and elevated blood pressure, AGT gene expression and secretion in adipose tissue were found to be stimulated by cyclic AMP via increased DNA cyclic AMP-responsive element- (CRE-) binding activity." (PMID 22500179, 2012). "Most data support an elevation of angiotensinogen mRNA expression in adipose tissue during obesity." (PMID 21410966, 2011). "Obesity causes a state of a chronic low-grade systemic inflammation, with elevated levels of certain circulating proinflammatory adipokines, such as TNF-α, IL−6, leptin, plasminogen activator inhibitor-1 (PAI-1), angiotensinogen, and CRP, as well as lower levels of adiponectin." (PMID 36555411, 2022). "In addition to the increased BMI, obesity is also connected with increased plasma volume, increased exchangeable sodium, increased plasma insulin resistance and secondary hyperinsulinemia, and increased hepatic synthesis of angiotensinogen." (PMID 35872884, 2022). "Hence, we hypothesize that adipose tissue enrichment of angiotensinogen leads to activation of inflammatory cascades and endoplasmic reticulum (ER) stress, thereby, contributing to obesity." (PMID 31186446, 2019). "Thus, we have hypothesized that the chronic oxidative/ inflammatory milieu of obesity will alter cellular transcriptional machinery that, in turn, will have haplotype-dependent effect on the AGT expression." (PMID 28467442, 2017). "Obesity resistance phenotype has been generated upon deletion of many receptors in these systems as well as of the AngII precursor molecule angiotensinogen, which corroborates the physiological relevance of these systems in the regulation of metabolic activity and body mass maintenance." (PMID 25926796, 2015). "HDAC1 binds to deacetylated c‐Myc at the renal angiotensinogen (Agt) gene promoter, upregulates Agt and ANG II levels, and participates in the pathogenesis of obesity‐related hypertension." (PMID 40497340, 2025). "Leptin stimulation of the sympathetic nervous system, hyperinsulinemia, and indigenous synthesis of angiotensinogen through adipocytes contribute to the promotion of hypertension in CKD and obesity." (PMID 36415443, 2022). "This study showing elevated plasma renin, together with suppressed angiotensinogen and reduced levels of ACE2 protein suggests RAS overactivation in PCOS occurs in an obesity-independent manner." (PMID 32838280, 2020). "The investigation of the AGT mutation’s influence on overweight/obesity deserves attention, as the RAS polymorphism’s detection could help to track patients at increased risk of developing obesity-associated conditions and allow the implementation of preventive measures to avoid unwanted outcomes." (PMID 31365628, 2019). "Individuals with obesity are often reported to have increased plasma renin and angiotensin converting enzyme (ACE) activities, plasma angiotensinogen (AGT), angiotensin II (ANG II), or aldosterone levels." (PMID 29540174, 2018). "Not only does adipose tissue have a local RAS but serum levels of all the components of the RAS [renin, angiotensinogen (AGT), angiotensin (ANG) converting enzyme] are elevated in obesity." (PMID 25120524, 2014). "Further, deletion of AGT and other RAS genes leads to lower fat mass and resistance to diet-induced obesity." (PMID 23308073, 2012). "Obesity and hypercholesterolemia have been shown to play a role in ACE gene expression, but also in other RAS intervenients, such as AGT or AT1R." (PMID 18637188, 2008). "Adipokines mainly involved in obesity and MetS are leptin, nonesterified free fatty acids, reactive oxygen species, adipocytic angiotensinogen, and resistin." (PMID 39411599, 2024).
Obesity (continued). "Obesity results in increased production of AGT, Ang II and aldosterone in PVAT." (PMID 36457800, 2022). "Although the increase in AGT levels during obesity would not seem to have a direct effect on β-cell mass, its metabolite Ang1-7 exerts beneficial effects on β-cell survival and identity." (PMID 35628332, 2022). "Indeed, genetic deletion of AGT, ACE, renin, AT1, or AT2 protects rodents from diet-induced obesity and insulin resistance." (PMID 23308073, 2012). "Angiotensinogen, renin (or peptides with renin-like activity), angiotensin converting enzyme (ACE), and AT1 and AT2 receptors are all secretory products of the rodent adipocyte, and the expression of some are increased in obesity." (PMID 22475205, 2012). "Notably, some possible mediators of obesity‐related SNS activation have been suggested, such as adipokines (like leptin, angiotensinogen, interleukin‐6, and tumor necrosis factor‐α), angiotensin II, hyperinsulinemia, impaired baroreceptor reflexes, and activated chemoreceptor reflexes." (PMID 35739356, 2022). "We were not able to find any associations between BMI and WC (overweight/obesity) and ACE and AGT polymorphisms, indicating that the RAS system might not be involved in overweight and obesity, at least based on genetic backgrounds." (PMID 31365628, 2019). "Negative angiotensinogen, Ang1-7, and des-Arg9-bradykinin correlations with BMI strongly imply reduced ACE2 activity in obesity." (PMID 40282897, 2025). "Interestingly, it has been hypothesized that angiotensinogen, produced even by adipocytes, may play a role in determining increased BP in obesity, even if there is a lack of studies showing a direct effect of angiotensinogen or angiotensin II on BP regulation in obesity." (PMID 31330870, 2019).